DGAT1 (diacylglycerol O-acyltransferase 1)
Diseases named in the same sentence as DGAT1 in open-access papers (continued):
Sharing a sentence is not in itself a finding about the gene and the disease.
Obesity (continued). "Overexpression of DGAT1 in skeletal muscle also increased TG storage in mice with diet-induced obesity and mimicked the “athlete's paradox” observed in endurance-trained humans; skeletal muscle DGAT1 transgenic mice had increased FA oxidation and improved insulin sensitivity." (PMID 24493834, 2014). "Collectively, our results provide pharmacological support for the hypothesis that the intestine is the key tissue in which DGAT1 plays a role in promoting obesity and insulin resistance when exposed to high fat food." (PMID 25405858, 2014). "Several small molecule DGAT1 inhibitors have been reported to ameliorate obesity in rodents." (PMID 23336002, 2013). "In addition, intestine-only DGAT1 reconstitution in DGAT1 knockout mice restored their sensitivity to diet-induced obesity." (PMID 23336002, 2013). "In triacylglycerol synthesis pathway, DGAT1 is not essential but seems to be better drug target for care of obesity because mice deficient in DGAT2 die shortly after birth." (PMID 22676350, 2012). "Due to their involvement in TG re-synthesis and secretion, it is believed that MOGAT2 and 3, but also DGAT1 are potential therapeutic drug targets for treating diet-induced dyslipidemia and obesity, whereas an activation of PPARα was suggested as the initial regulator." (PMID 23241455, 2012). "Hence, DGAT1 is considered a potential therapeutic target for treating obesity and related metabolic disorders." (PMID 22073239, 2011). "Since there are limited data on the phenotype of heterozygote (Dgat1+/-) mice, these were included in the study to give some perspective on how much inhibition of DGAT1 might be required to treat obesity and type 2 diabetes." (PMID 17239230, 2007). "Previous reports have described resistance to diet-induced obesity and amelioration of obesity due to the Ay, but not the Lepob or LepRdb, mutation in DGAT1-deficient (Dgat1-/-) mice." (PMID 17239230, 2007). "Besides, obesity and metabolic syndrome were associated with further accumulation of TAG, DAG, and FFA in the cells that stemmed from subADMSCs accompanied by an increase in FASN and DGAT1 protein expression." (PMID 35563741, 2022). "However, Dgat1 KO mice are viable, generally lean, and resistant to diet-induced obesity." (PMID 31786011, 2020). "Others have reported that increasing diacylglycerol acyl transferase 1 (DGAT1) expression increases murine macrophage capacity for TG storage, protects against FA‐induced inflammatory activation and is sufficient to reduce the inflammatory and metabolic consequences of diet‐induced obesity." (PMID 26522807, 2016). "DGAT1 plays a role in VLDL synthesis; increased plasma VLDL concentrations may promote obesity and thus DGAT1 is considered a potential therapeutic target of obesity and associated complications." (PMID 25184241, 2014). "However, overexpression of DGAT1 in adipose tissue of C57Bl/6 mice was associated with obesity but not with impaired glucose disposal." (PMID 17239230, 2007). "On SAT, a reduction in fatty acid-binding protein (FABP), diacylglycerol O-acyltransferase 1 (DGAT1), and HSL mRNA levels were observed in pregnant women with obesity on partum day, indicating that both lipolysis and lipogenesis are reduced." (PMID 39083072, 2024). "Currently, clinical trials of DGAT1 and DGAT2 inhibitors for obesity, diabetes, and other metabolic disorders are being tested as a single agent or in combination with another metabolic regulatory drugs, such as acetyl-CoA carboxylase inhibitors." (PMID 38500157, 2024). "It is suggested that DGAT1 participates in the synthesis of very low-density protein (VLDL) and is involved in obesity and insulin resistance." (PMID 34095320, 2021). "Surprisingly, SCD1, DGAT1 and EBP were downregulated by LPS, as LPS have previously been described to initiate obesity." (PMID 27438462, 2016).
Obesity (continued). "However, DGAT1 null mice exhibit skin aberrations, presumably due to depletion of essential lipids within the skin, and thus the DGAT1 inhibitor could induce skin aberrations when systemically administered for the treatment of obesity and diabetes." (PMID 25405858, 2014). "Despite a number of previous studies on the DGAT1 and DGAT2 genes, which have emphasized their importance as potential obesity treatment targets to increase triacylglycerol accumulation, little is known about their evolutionary timeline in eukaryotes." (PMID 21933415, 2011). "As mice lacking DGAT‐1 show resistance to weight gain and improved insulin sensitivity, the enzyme has been proposed as potential target for treating obesity and obesity‐related illnesses in humans." (PMID 40386326, 2025). "Importantly, obesity enhances the expression of the key enzymes responsible for fatty acid synthesis (FASN), triglyceride synthesis (DGAT1), and lipid oxidation (β-HAD) in both subADMSCs- and visADMSCs-derived adipocytes." (PMID 37602323, 2023). "Notably, after restoring the function of intestinal DGAT1 in Dgat1−/−mice, the resistance to HFD-induced hepatic steatosis and obesity disappeared." (PMID 36817150, 2023). "Pharmacological inhibition of DGAT1 showed lipid lowering effect and reduced body weight in high-fat diet induced obesity mice without apparent liver damage." (PMID 30037134, 2018). "Our data indicate that maximal inhibition of DGAT1 may be required for efficacy and suggest a potential strategy of combining with DPP-4 inhibitors for the treatment of obesity and diabetes." (PMID 23336002, 2013). "Mice lacking DGAT1 have increased energy expenditure and insulin sensitivity and are protected against diet-induced obesity and glucose intolerance." (PMID 16448557, 2006). "In contrast, transplantation of WT adipose tissue into Dgat1-/- mice did not adversely affect their resistance to diet-induced obesity or enhanced response to insulin." (PMID 16448557, 2006). "Although both DGAT1 and DGAT2 catalyze the same reaction in the last step of triglyceride synthesis, often in the same cells, DGAT1 but not DGAT2 has been pursued for more than a decade as a therapeutic target for obesity and metabolic disorders such as insulin resistance." (PMID 31345219, 2019). "Furthermore, it has been shown that obesity resistance of Dgat1−/− mice was due to the absence of intestinal Dgat1 expression." (PMID 28706193, 2017). "In clinical trials, DGAT1 inhibitors have not shown precise anti-obesity and anti-diabetic effects, because the drug doses are limited, at least in part, due to lack of an adequate therapeutic window between the efficacy dose and the dose causing the GI adverse effects." (PMID 26938273, 2016). "Thus, the DGAT1 inhibitor is expected to become a novel treatment option for obesity and type-2 diabetes mellitus (T2DM) without the severe adverse events associated with the DGAT2 inhibition." (PMID 25405858, 2014). "This work determined whether the intestine-targeted DGAT1 inhibitor could improve obesity and insulin resistance without skin aberrations in mice." (PMID 25405858, 2014). "In addition to the metabolic phenotypes of DGAT1 null mice such as resistance to hepatic steatosis and diet-induced obesity, they exhibit skin aberrations owing to lack of DGAT1 in the skin." (PMID 25405858, 2014). "Since there is a report that Compound A shows beneficial metabolic effects, we focused on whether the predominantly intestine-targeted DGAT1 inhibitor could improve obesity and insulin resistance without skin aberrations in mice in the present study." (PMID 25405858, 2014). "Thus, DGAT1 inhibitor monotherapy is unlikely to have sufficient therapeutic margin to treat obesity and diabetes." (PMID 23336002, 2013).
Obesity (continued). "Here we show that partial DGAT1 deficiency in mice suppressed postprandial triglyceridemia, led to elevations in glucagon-like peptide-1 (GLP-1) and peptide YY (PYY) only following meals with very high lipid content, and did not protect from diet-induced obesity." (PMID 23336002, 2013). "Further study of the regulatory mechanisms of DGAT1 phosphorylation would provide valuable information for screening and developing drugs to lower ectopic TAG storage in non-adipocyte tissue, with implications for diabetes, obesity, and related metabolic disorders." (PMID 26942218, 2015).
Hepatic steatosis (43 papers, 2010 to 2025). Steatosis is a term used to denote lipid accumulation within hepatocytes. "This study demonstrates that ghrelin deletion prevents age‐associated hepatic steatosis through downregulation of the p300/C‐EBPα/β/DGAT1 pathway." (PMID 29024407, 2018). "Levels of the key enzymes DGAT1 were significantly upregulated with aging in WT animals but not in the KO, suggesting that ghrelin deletion prevents aging‐associated hepatic steatosis by downregulating this pathway." (PMID 29024407, 2018). "Previous research on DGAT1-/- mice demonstrated that DGAT1 was required for hepatic steatosis caused by a high-fat diet or fasting, both of which promote hepatic uptake of exogenous FAs, but not for hepatic steatosis caused by upregulation of endogenous de novo FA synthesis." (PMID 35140289, 2022). "Accordingly, pharmacologic inhibition of Dgat1, a key enzyme of TG synthesis, with antisense oligonucleotides protected against hepatic steatosis in mice fed a high-fat diet." (PMID 40608687, 2025). "Inhibiting diacylglycerol acetyltransferase (DGAT1, DGAT2) enzymes (iDGAT1, iDGAT2), involved in triglyceride (TG) synthesis, improves hepatic steatosis in metabolic dysfunction-associated steatotic liver disease (MASLD) patients." (PMID 39201759, 2024). "In the context of ALD, both Dgat1 and Dgat2 have been shown to be induced in the alcohol-exposed liver leading to hepatic steatosis." (PMID 35864895, 2022). "This study demonstrated that miR-30c-5p down-regulated DGAT1 expression and therefore reduced exogenous fatty acids esterification to prevent hepatic steatosis." (PMID 28088781, 2017). "Alike, miR-26b-5p influences translation of caveolin 2 and diacylglycerol O-acyltransferase 1, i.e. a key enzyme in hepatic steatosis in addition to lecithin-cholesterol acyltransferase which catalyzes its esterification for cholesterol transport." (PMID 27045805, 2016). "Tang’s study revealed that Lusisnthriding, derived from dendrobium, can stimulate the activation of FXR, thereby mitigating hepatic steatosis in mice on a high-fat diet by suppressing the expression of fatty acid synthesis genes, such as Srebp1c, Fas, Scd-1, Dgat1, and Lpin1." (PMID 39769418, 2024). "Altogether, our results indicated that the improvement of MetS and hepatic steatosis by LWE could be attributed to the activation of the SIRT6/SREBP1 /FAS/DGAT1 pathway to reduce lipogenesis." (PMID 35681388, 2022). "Reduced expression of DGAT1 is reported to be an effective way to prevent hepatic steatosis." (PMID 31340583, 2019). "In addition to changes in hepatic steatosis, we regularly observed that the coats of treated animals were drier, consistent with reduction in triglycerides, as has been observed in the DGAT1 mouse knockout with dry coat." (PMID 30359371, 2018). "The beneficial metabolic effects of Compound B may, at least partly, be ascribed to suppressed fat absorption from the intestine via inhibited intestinal DGAT1, as postprandial hyperlipidemia is assumed to promote hepatic steatosis and insulin resistance." (PMID 25405858, 2014). "Interestingly, intestine selective overexpression of DGAT1 in the context of mice null for DGAT1 reverses the lean phenotype and hepatic steatosis suggestive that DGAT1 expression in intestine is a major contributor to metabolic phenotype." (PMID 22073239, 2011). "While down-regulation of DGAT1 in spheroids following LGALS3 silencing could have protective effects in condition of hepatic steatosis, changes in CPT1A and PPARA mRNA levels, might be a consequence of the lipid content reduction or represent an independent effect exerted by Gal-3." (PMID 40608687, 2025). "However, SR treatment attenuated HFD-induced hepatic steatosis by suppressing TG contents and the expression of fatty acid transport- and lipogenesis-related genes including Fabp1, Fabp4, Slc27a5, Pparg, Mlxipl, Srebf1, Srebf2, Fas, Dgat1, and Dgat2." (PMID 35454963, 2022).
Hepatic steatosis (continued). "Based on these studies of C/EBPα‐p300 complexes and data of ChIP assay, we conclude that the C/EBPα‐p300 complexes are not accumulated in old KO mice and that this leads to the lack of activation of the DGAT1 promoter and prevention of hepatic steatosis associated with aging." (PMID 29024407, 2018). "Moreover, obese animals showed higher (P < 0.05) transcript levels of the lipogenic genes Pparg, Srebf1, Mogat2 and Dgat1 as well as a moderate-to-severe hepatic steatosis evidenced by the staining of the lipid droplet-coating protein adipophilin in liver sections." (PMID 28008992, 2016). "DGAT1 is a key enzyme in lipid homeostasis, and in MASLD, its overactivity drives excessive lipid production, contributing to hepatic steatosis and to metabolic disturbances like lipotoxicity, oxidative stress, and inflammation." (PMID 40219006, 2025). "Specifically, genetic deletion or pharmacological DGAT1 and DGAT2 inhibition reduced hepatic steatosis and hypertriglyceridemia in murine models and MASLD patients (NCT01811472)." (PMID 39201759, 2024). "Cichoric acid plays an important role in reducing hepatic steatosis, as it reduces the expression of lipogenic actors, such as SREBP-1c, DGAT1, FAS, and SCD-1, and also of inflammatory factors such as IL-6, IL-1b, NF-κB, and TNF-α." (PMID 39458995, 2024). "The enzymes DGAT1 and DGAT2, involved in the final step of triacylglycerol synthesis, also play a role in developing hepatic steatosis." (PMID 39275255, 2024). "Altogether our results suggest that a greater induction of PEMT in patients with genotype 3 infection promotes more hepatic steatosis, through the downstream effects on MTP, SREBP 1-c, DGAT1 and other key lipid genes." (PMID 37240132, 2023). "Hepatic gene expression analyses revealed that lipogenic gene expression (i.e., Cd36, Dgat-1, Fasn, Srebp1-c, Pgc-a1, Lpl, Ppary) was significantly lower in absence of MIF, providing a possible rationale for the observed reduction in hepatic steatosis." (PMID 26124760, 2015). "However, another research showed that deficiency of DGAT1 did not protect db/db mice against hepatic steatosis, which indicated that excessive triglyceride accumulations in liver of db/db mice may result from not only enhanced exogenous, but also endogenous fatty acids synthesis." (PMID 28088781, 2017). "Suppression of diacylglycerol acyltransferase-2 (DGAT2), but not DGAT1, with antisense oligonucleotides reversed diet-induced hepatic steatosis and insulin resistance, suggesting that PNPLA3-mediated lipid accumulation is possibly associated with DGAT2 signaling." (PMID 39000384, 2024). "Therefore, increasing the expression of SIRT6 and suppressing the expression of SREBP-1/FAS/DGAT1 may be part of the mechanism of LWE-alleviated MetS and hepatic steatosis in Lepr−/− rats." (PMID 35681388, 2022). "In addition, Dgat2 ASO treatment in rats with diet-induced hepatic steatosis was shown to reduce hepatic diacylglycerol and TG contents, but Dgat1 ASO treatment did not reduce either." (PMID 27266874, 2016). "Mice lacking DGAT1 have reduced tissue TG levels and are protected against hepatic steatosis." (PMID 25887406, 2015).
Insulin resistance (31 papers, 2010 to 2025). Increased resistance towards insulin, that is, diminished effectiveness of insulin in reducing blood glucose levels. "DGAT1 overexpression in skeletal muscles protected mice from high fat diet-induced insulin resistance, while DGAT1 deficiency diminished insulin sensitivity." (PMID 37684349, 2023). "Our results showed LE increased PPARγ, GLUT4 and DGAT-1 levels, demonstrating the potential of this lemon extract in the management of insulin resistance conditions associated with TNF-α pathway activation." (PMID 34361563, 2021). "In contrast, however, the inhibition of DGAT1 activities in the skeletal muscle or macrophage may cause insulin resistance, leading to aggravation of metabolic disorders, as a result of inhibited conversion of fatty acids substrates which induce insulin resistance into the form of triglyceride." (PMID 25405858, 2014). "The upregulation of muscle-specific Dgat1 increased triglyceride synthesis in skeletal muscles and attenuated diet fat-induced insulin resistance." (PMID 37644753, 2023). "Deletion or knockdown of either DGAT1 or DGAT2 provokes DG accumulation at the ER, which has been tightly linked to lipotoxicity, ER stress, and the development of insulin resistance." (PMID 33872605, 2021). "Additionally, genetic alterations in these genes are strongly involved, especially mutations in five genes (DGAT1, FASN, LPL, IRS2, and YWHAZ), in lipid synthesis, insulin resistance, and cancer progression." (PMID 31717414, 2019). "Moreover, hepatic DGAT2 merits further attention as a parallel, or possibly alternative, drug target to DGAT1 for improving insulin resistance and reducing body weight." (PMID 31345219, 2019). "Furthermore, transgenic overexpression of myocellular DGAT1 reduces high-fat diet-induced insulin resistance in mice." (PMID 30081476, 2018). "In agreement with our hypothesis that increasing the lipogenic capacity of skeletal muscle can improve insulin sensitivity, the results of the present study indicate that DGAT1 overexpression did improve skeletal muscle insulin resistance." (PMID 21264296, 2011). "By converting fatty acyl-CoA and DAG into TAG, DGAT1 is considered to modulate the levels of the lipotoxic fatty acid derivate DAG, which is marked as a possible causative fatty acid intermediate in the onset of insulin resistance." (PMID 21264296, 2011). "These compounds alleviated lipid accumulation and insulin resistance in HepG2 cells through the elevation in PI3K expression and the phosphorylations of Akt and AMPK, and reduction in the expressions of DGAT1 and SCD." (PMID 31340583, 2019). "It has also been shown that elevated DGAT1 expression in macrophages increases their capacity for TAG storage and protects from diet-induced insulin resistance and inflammation." (PMID 30081476, 2018). "This study implied a function role of DGAT1 in the synthesis of TAG, insulin resistance, and IMF deposition." (PMID 28386555, 2017). "In conclusion, this study has shown for the first time that the intestine-targeted delivery of the DGAT1 inhibitor improves postprandial hyperlipidemia, body adiposity, hepatic lipid accumulation and insulin resistance without skin aberrations." (PMID 25405858, 2014). "Similarly, mice overexpressing DGAT1 or DGAT2 in the liver develop steatosis but do not show any defects in insulin sensitivity and signalling, suggesting that lipid accumulation in the liver is not sufficient to cause insulin resistance." (PMID 30081476, 2018). "Moreover, DGAT2 could not compensate for the loss of DGAT1 in adipose tissue, demonstrated by the fact that DGAT1, but not DGAT2 deletion in combination with a HFD leads to ER stress, lipotoxicity, and systemic physiological changes such as insulin resistance." (PMID 40083687, 2025). "Taken together, the results indicate that the olive oil intake mimicked part of the exercise-induced effect via the DGAT1 cascade, explaining why the increase in IMTG did not lead to insulin resistance." (PMID 33916004, 2021).